STAT1 (signal transducer and activator of transcription 1)
Diseases named in the same sentence as STAT1 in open-access papers (continued):
Sharing a sentence is not in itself a finding about the gene and the disease.
infection (continued). "Following infection lysates of these cells were assessed for STAT1 phosphorylation." (PMID 18989459, 2008). "Furthermore, exogenous IFN fails to significantly augment this activation in the setting of infection with B.anthracis suggesting a potential for STAT1 independent IFN signaling." (PMID 17710136, 2007). "Furthermore, STAT1 deficiency markedly reduced proportions of IFN-γ-producing CD8+ T cells and interleukin-10-producing CD4+ T cells at day 7 post-infection." (PMID 41910261, 2026). "Although the molecular interactions governing PgV species-tropism remain unknown, the unique susceptibility of innate-immune-compromised (STAT1-/- and IFNAR-/-) mice to RPgV suggests that innate immune effectors contribute to restrict cross-species PgV infection." (PMID 39196893, 2024). "During the acute infection stage, there is an increase in neuronal cell death, the activation and infiltration of microglia, the expression of both inflammatory and anti-inflammatory cytokines, and Stat1 phosphorylation, as well as enhanced microglia reactivity and associated gene transcripts." (PMID 39061995, 2024). "No sex difference was found in NK cells among B6, Stat1ko, and CCR2ko mice (p > 0.05, Mann–Whitney rank sum test), suggesting that accumulation of NK cells in the tongue is not differentially regulated in normal and CCR2- or Stat1-deficient mice during viral control of MmuPV1 infection." (PMID 38133335, 2023). "In the current study, we use genetically modified mice to target CCR2 and Stat1 pathways, with the aim of investigating the role of both innate and adaptive immune responses in clearing oral papillomavirus, using our established papillomavirus (MmuPV1) infection model." (PMID 38133335, 2023). "Thus, STAT1 GOF mimics some aspects of infection-induced Tfh differentiation." (PMID 37275873, 2023). "In this study, the expression of STAT1 was significantly decreased, suggesting that after tachyzoite infection in astrocytes, the down-regulated STAT1 might participate in promoting the transformation of tachyzoites to bradyzoites, as well as inhibiting the persistent infection of tachyzoites." (PMID 37721957, 2023). "Interestingly, STAT1 was increased during infection in DEVs from KO BMDCs." (PMID 36131943, 2022). "During E30 infection, genes associated with the type I IFN signaling pathway (Isg15, Mx1, Mx2, Sp100, Ifit1, Ifit3, Ifih1, Irf7, Irf9, guanylate-binding proteins 2 [Gbp2], and Stat1) and defense response to viruses (Ddx58, Ddx60, Zbp1, Oas2, Nlrc5, and Eif2ak2) were significantly upregulated." (PMID 36147849, 2022). "Of note, in the context of C. rodentium infection, STAT3 was described as an essential player for the intestinal epithelium to restrict infection by suppressing cell death to maintain intestinal integrity, which might be an alternative hypothesis for reduced STAT1 phosphorylation." (PMID 34497340, 2022). "Additionally, only the infection with wild type virus showed a degradation of STAT1 protein." (PMID 35632848, 2022). "Thus, whether blocking STAT1 activity with fludarabine could increase PeV-A3 infection was investigated." (PMID 35891479, 2022). "STAT1 plays a key role in the immunoglobulin class-switch recombination through the upregulation of T-bet; it also plays a key role in the production of T-bet+ memory B cells that contribute to tissue-resident humoral memory by mounting an IgG response during re-infection." (PMID 35456913, 2022). "Rapid migration of STAT1-sufficient microglia to sites of lytic tachyzoite egress may thus position these cells to serve as an immunological “cellular buffer” – becoming actively infected and subsequently clearing intracellular infection via STAT1-dependent cytosolic killing molecules." (PMID 36067217, 2022). "Thus, similar to macrophages from STAT1-/- mice, the absence of M1-/- in macrophages also makes them more susceptible to infection than macrophages from WT mice." (PMID 34653236, 2021).
infection (continued). "Importantly, only CR6F514I infection of Stat1-/- mice was detectable in the brain at 5 dpi." (PMID 33705489, 2021). "Since functional analysis of genes upregulated at the presymptomatic (3 dpi) stage of WNV-ND showed that some of genes (MX1 and STAT1) have a dual immune-neural functionality (i.e., being pleiotropic), we next sought to determine whether the number of such genes increased as infection progressed." (PMID 33599611, 2021). "Furthermore, only STAT1+/+ mice developed M2 macrophages at 8 weeks post-infection, although macrophages from both T. crassiceps-infected STAT1+/+ and STAT1−/− mice responded to IL-4 in vitro, and both groups of mice were able to produce the Th2 cytokine IL-13." (PMID 34684235, 2021). "However, it seems unlikely that IL-5 has an instrumental role in the lethality of LCMV-infected STAT1 KO mice since STAT1/RAG1 DKO mice had greater IL-5 levels than STAT1 KO mice following infection, suggesting that adaptive immune cells inhibit the production of IL-5." (PMID 32310998, 2020). "The high IL-5 levels seen in STAT1 KO and STAT1/RAG DKO mice may contribute to early weight loss and more severe thickening of the basement membrane of bronchial epithelial cells, which was exaggerated in STAT1/RAG1 DKO mice compared with STAT1 KO mice following infection." (PMID 32310998, 2020). "Moreover, mice lacking adaptive immunity owing to RAG deficiencies (no T cells or B cells) are protected against severe SARS-CoV disease, whereas mice genetically devoid of STAT-1, an important molecule involved in innate immunity, are sensitive to infection by SARS-CoV." (PMID 32841215, 2020). "Interestingly, loss of STAT1 in macrophages failed to completely protect mice from dysbiosis, with an obvious shift in microbiome composition still evident after infection, albeit reduced in comparison to infected WT mice." (PMID 31138751, 2019). "It is also in agreement with later studies describing the phenomenon of mice with a homozygous mutation Y701F STAT1, which were more susceptible to infection than STAT1-null mice and were not able to develop a similar type of STAT2/IRF9-mediated response to IFN as seen in STAT1-null mice." (PMID 29892288, 2018). "Therefore, we speculated that the gradual loss of the IFN-γ antiviral effect in BMMs is due to the reduction in STAT1 phosphorylation that occurs during MHV-68 infection." (PMID 30075008, 2018). "Together, these data indicate that the absence of STAT1 in astrocytes does not impact the initial recruitment of immune cells to the brain, but similarly to other infections, elevated parasite burdens in the CNS are associated with increased T cell recruitment but decreased effector functions." (PMID 27834206, 2016). "This lower Stat1 expression may explain in our system the observation of diminished type II IFN inducible gene expression in the Ifnar1-/- compared to the WT following infection." (PMID 26918359, 2016). "Interestingly, HPeV1 was notable to induce STAT1 activation in either cell type, which may beimportant for HPeV1 infection via modulating the IFN signaling pathway." (PMID 25646764, 2015). "Knockout mice lacking the receptor for interferon-α and β (IFN-α/βR−/−) or the cytoplasmic Signal Transducer and Activator of Transcription-1 (STAT1) protein are susceptible to infection by a wide range of filoviruses that do not cause disease in wild-type mice." (PMID 23170168, 2012). "Although lack of Stat1 signaling in non-hematopoietic cells or DC does not per se affect survival and clearance of infection, it may synergize with the Stat1 deficiencies of other cell types to produce the more severe outcome of the complete Stat1 knockout." (PMID 22719255, 2012).
infection (continued). "While the amount of serum cytokines generally followed the severity of infection in different Stat1 genotypes, IL12 was the exception because it was strongly increased in mice with Stat1-deficiency outside the hematopoietic compartment that were able to cope with infection nearly as well as WT mice." (PMID 22719255, 2012). "Furthermore, in either WT-5 or KR-2 cells, infection with HSV hardly induced any STAT1 phosphorylation indicating that an increase in IFNAR1 degron phosphorylation may not rely on HSV-induced production of Type I IFN." (PMID 21695243, 2011). "Moreover, a reciprocal build up between IRF and IFN in the later stages of infection may contribute to the changes of gene expression and STAT1 activation." (PMID 19404407, 2009). "Incidentally, a recent study showed that phagosome acidification is defective in Stat1−/− macrophages and this correlated with an increased survival of L. major promastigotes, suggesting a role for acidic pH in the control of intracellular Leishmania growth early during infection." (PMID 19834555, 2009). "Consistently, physalin F inhibited SeV-induced phosphorylation of IRF3 at Ser386 (IRF3S386), STAT1 at Y701 (STAT1Y701), and STAT2 at Y690 (STAT2Y690) at 8 h post-infection in HEK293T cells." (PMID 41599057, 2026). "In the STAT1 knockdown experiment, the viral products were elevated in the conventional HBV-transfected HepG2 cells but decreased in the primary human hepatocyte infection system." (PMID 40048440, 2025). "Compared with ASFV-Δ4R infection, ASFV-WT infection consistently decreased the binding of STAT1, STAT2 and IRF9." (PMID 40618140, 2025). "Viral replication did not alter IFNAR expression but led to reduced phosphorylation of STAT1, as well as both degradation and reduced phosphorylation of STAT2, similarly to DENV-infection." (PMID 41477009, 2025). "We further observed that STAT1 phosphorylation in HMPV-infected macrophages peaks at later time points (20–24 h), whereas p38 MAPK phosphorylation occurs as early as 1 h post-infection and remains sustained, both in MDMs and THP-1 cells." (PMID 41346628, 2025). "Both Western blot and grayscale analysis showed that ARCN1 knockdown markedly increased IKKε protein abundance upon infection, accompanied by elevated phosphorylation of IRF3, STAT1, and STAT2." (PMID 41343552, 2025). "Phosphorylation of STAT1, STAT3, IκBα, and NF-κB p65 was detected as early as 6 hours post-infection (hpi) and peaked at 24 hpi." (PMID 41281739, 2025). "By 48 h of infection in A549 control cells, there was a corresponding increase in PIV5 NP expression, STAT1 was undetectable and MxA expression was reduced." (PMID 39931755, 2025). "We observed that the knockdown of LINC2781 significantly reduced the expression of STAT1/p-STAT1 and the downstream JAK-STAT pathway IRF9 protein in CVB5-infected cells after 24 h post-infection." (PMID 40626722, 2025). "Upon infection with A/WSN/33 or interferon treatment, A549 cells show increased phosphorylation of STAT1, STAT2, and NF-κB." (PMID 40434103, 2025). "In conclusion, knockdown of the host gene STAT1 showed antiviral activity in conventional HBV-transfected HepG2 cells, but conversely decreased viral replication in a primary human hepatocyte infection system." (PMID 40048440, 2025). "Consistently, compared with infection with ASFV-WT, infection with ASFV-Δ4R increased nuclear translocations of phosphorylated STAT1, phosphorylated STAT2, and IRF9 in PAMs." (PMID 40618140, 2025). "Regardless of the dose, all Ifnar1-/- and Stat1-/- mice experienced incremental weight loss, increasing clinical signs, and ultimately succumbed to lethal infection between 5–6 dpi and 6–8 dpi, respectively, in sharp contrast to wild-type mice of which 100% survived infection with 103 FFU of USUV." (PMID 40694555, 2025). "Upon activation during infection, IFIH1 can also promote STAT1 transcription, facilitating M1 polarization in macrophages and intensifying inflammation." (PMID 40625749, 2025).
infection (continued). "At 16 h post FMDV infection, we found that PLA2G16-overexpressing cells phosphorylated STAT1 substantially more than wild-type cells in our analysis of important nodes in the innate immune signaling cascade." (PMID 40733501, 2025). "Top downregulated DEGs in bystander cells indicated a decreased enrichment of certain pro-inflammatory cytokines and signaling molecules in ADE compared to conventional infection conditions, including CXCL11, CXCL10, CCL2, DOCK4, STAT1, and JAK2." (PMID 39902963, 2025). "Comparing infection-induced TCRab+ T cells, adults exhibited higher average STAT3, SOCS1, and SOCS3 expression, whereas STAT1 and STAT2 were elevated in cells from infected children, highlighting divergent IFN signaling with age." (PMID 40834853, 2025). "The phosphorylation of STAT1 (pSTAT1), a canonical downstream effector of type I IFN signaling, was markedly reduced in Ifnar1–/– pBMDMs following MPXV infection, confirming the effective disruption of IFNAR1-dependent signaling in these cells." (PMID 41225161, 2025). "In cells incubated with both microorganisms and infected with rotavirus (pre-infection), we observed a significant (p < 0.05) upregulation of the mRNA levels of SOCS3, IFN-γ, STAT1, and IL-10." (PMID 38791551, 2024). "While Mtb CDC1551 infection significantly upregulated the expression of IL8, expression of TLR4, PPARG, and STAT1 was significantly upregulated in Mtb HN878-infected trained and restimulated macrophages, compared to the cells without restimulation." (PMID 38980014, 2024). "3Cpro utilizes its protease activity to cleave STAT1 and STAT2, thereby diminishing the host IFN response to promote SVA infection." (PMID 38869319, 2024). "Two mRNAs were down-regulated in all treatment groups at the later time points post-infection, namely, CNTNAP1 and NR4A1, while twenty mRNAs were up-regulated in all later time point treatment groups, including IFI6, LY6E, MX1, OASL, STAT1, and CMPK2." (PMID 38675946, 2024). "Further IFN and antiviral related proteins were upregulated upon infection with PeV-A3 (EIF2AK2, STAT1), or PeV-A1 (NCAM1, POM121), and downregulated upon PeV-A1 infection (EIF4G1, UBE2N, RANBP2, FLNA)." (PMID 38514653, 2024). "Increased Orf6 levels suppressed host innate responses to infection by decreasing IRF3 and STAT1 signalling measured by transcription factor phosphorylation and nuclear translocation." (PMID 38228858, 2024). "Given that ΔUL26 infection fails to block the expression of cytokine signaling genes, we assessed whether the inactivation of STAT1 or RELA, endpoint transcription factors associated with activated STAT and NFκB signaling, respectively, would rescue ΔUL26 replication defects." (PMID 38768227, 2024). "To determine the effect of C. sorokiniana in HT-29 cells, we studied the mRNA levels of IFN-γ, IL-10, SOCS3, STAT1, and STAT2 genes in cells incubated with C. sorokiniana in the rotavirus pre- and post-infection assays." (PMID 38791551, 2024). "At 2 days post-infection, the cells were treated with 10 μM MG132 for 24 h and then the protein level of STAT1 was analyzed." (PMID 38018976, 2024). "In line with the suppression of the type I interferon response, TPF treatment led to a reduction in the activation (indicated by phosphorylation) of both STAT1 (signal transducer and activator of transcription 1) and STAT2, observed 24 h post-infection." (PMID 38932212, 2024). "In the CSFV infection groups, compared with mock, CSFV replicated in both normal PK-15 cells and STAT1-knockout PK-15 cells." (PMID 39539545, 2024). "In the CSFV infection groups, compared with mock, CSFV replicated in both normal 3D4/21 cells and STAT1-knockout 3D4/21 cells." (PMID 39539545, 2024). "STAT1-/-STAT2-/-mice succumb in early infection, indicating the resistance of the STAT1/2-mediated IFN signalling pathway to DENV-2 (strains S221, 16681, D2S10) infection." (PMID 39312399, 2024).
infection (continued). "Our findings corroborate that the degradation of STAT1 and IRF3, inhibiting intracellular IFN expression, enhances the infection efficacy of C. trachomatis." (PMID 39210513, 2024). "On the other hand, in the pre-infection assays with C. sorokiniana, the mRNA levels of SOCS3 and IFN-γ were increased, whereas in the post-infection assays, SOCS3, STAT1, and STAT2 were upregulated." (PMID 38791551, 2024). "WB analysis of mouse brains revealed higher levels of p-STAT1, IRF1, and PD-L1 in the brainstem of ECM mice, which increased with infection time." (PMID 38715061, 2024). "3D4/21 cells knockout for STAT1 showed increased LC3 levels compared to normal 3D4/21 cells, with LC3-I transformation to LC3-II protein observed at 24 hours post infection (hpi)." (PMID 39539545, 2024). "Deletion of Orf6 in BA.5 also increased the degree of infection-induced IRF3 and STAT1 phosphorylation and nuclear translocation." (PMID 38228858, 2024). "Given the pivotal roles of STAT1 and STAT2 in the IFN response signaling pathway, viruses have evolved various means to subvert their functions for establishing infection." (PMID 38869319, 2024). "The Jak-STAT signaling molecule STAT1 gene was significantly (p value < 0.005) upregulated at both 36 and 48 hpi in ALI-PRECs following infection with PHEV." (PMID 38932231, 2024). "Therefore, infection by parasites activates the iNOS/OPN/STAT1 pathway, suggesting that parasite-induced iNOS activation might contribute to parasite persistence in macrophages, potentially through the inhibition of the NLRP3 inflammasome by iNOS and our unpublished observations)." (PMID 39436890, 2024). "We identified important genes DE in both our in vitro and in vivo infection models consistent with previous studies, namely, TLR3, IFIH1 (MDA5), SOCS1, OASL, DDX60, STAT1, MX1, CMPK2, LY96 (MD-2), STAT1, STAT2, TRIM25, IRF7, and IFIT5." (PMID 38675946, 2024). "Nonetheless, they noted a moderate immune polarization on the Th1 side by the expression of IL-2, IL-12, IFN-γ, and transcriptional factors (STAT1 and STAT4) upon infection of dendritic cells with L. tarentolae expressing the SARS-CoV-2 full-length S." (PMID 39817166, 2024). "T. gondii type I (BK) can suppress the tyrosine phosphorylation of STAT1 in host cells, while infection with type I (RH), type II (PRU), and type III (CL14) can induce the degradation of phosphorylated STAT1 in the nucleus of host cells." (PMID 38003154, 2023). "miR146a-5p was predicted to be a negative regulator of B. burgdorferi-induced inflammation in early infection with mRNA targets including TLR2, STAT1, ICAM1, and IL6." (PMID 37319241, 2023). "Along with STAT1, MX1 and ISG15 were upregulated in the present study, similar to HUVEC cells after infection by Rickettsia conorii bacterium." (PMID 37384298, 2023). "As a result, we have focused on four down-regulated and immune-related proteins including STAT1, GBP4, IFIT3 and DDX58 after tachyzoite infection." (PMID 37721957, 2023). "NS4 of AHSV is an important virulence factor that suppresses host innate immunity during the early stages of infection by interfering with the JAK-STAT pathway and blocking the nuclear accumulation of STAT1." (PMID 37766314, 2023). "Highly activated TFs include STAT1, STAT2, and IRF3, which are responsible for innate and acquired immune responses and host defenses against infection." (PMID 38042877, 2023). "We observed that knockout of PL1pro-N promoted the phosphorylation of STAT1 at various time points after IBV infection and the nuclear translocation of pSTAT1 at 20 h post-infection." (PMID 38087313, 2023). "This overexpression took place at the early stages of infection and was type-I IFN- and STAT1-dependent." (PMID 38003837, 2023).